FUT2 (fucosyltransferase 2 (H blood group))
Diseases named in the same sentence as FUT2 in open-access papers (continued):
Sharing a sentence is not in itself a finding about the gene and the disease.
tumor (27 papers, 2016 to 2025). "The risk score of all tumor samples was counted as follows: Risk score = (0.974* B4GALT3) + (0.418* PYGL) + (0.195* GALNT14) + (−0.413* FUT2) + (−0.886* GALNT16)." (PMID 38244579, 2024). "Among these tumor associated glycans, the terminal alpha 1, 2-linked fucose of Lewisy and Globo H are synthesized by alpha 1, 2 fucosyltransferase, FUT1 and FUT2, in human." (PMID 30854233, 2019). "We observed a significant increase in the expression of FUT2 in the cE01, cE04, cE05, cE07, and cE09 subsets in normal colon samples and cE01, cE02, cE03, cE06, and cE08 subsets in tumor colon samples." (PMID 38456503, 2024). "Data (275 CRC tissues and 45 normal colon tissues) from TCGA database were analyzed and revealed that Fut2 expression was reduced in CRC tissues compared to non-tumor tissues." (PMID 36739428, 2023). "Overexpression of Fut2 inhibited cell proliferation, invasion and tumor metastasis in vivo and in vitro in SW480 and HCT116 cells." (PMID 36739428, 2023). "The results showed that Fut2 mRNA and protein levels were significantly downregulated in tumor tissues compared to the adjacent tissues in both humans and mice (p < 0.05)." (PMID 36739428, 2023). "Immunohistochemical analysis showed that animals injected with Fut2-overexxpressed cells had a lower percentage proliferation of Ki67 + tumor cells than mice administered WT control cells." (PMID 36739428, 2023). "Meanwhile, mRNA and protein levels of Fut2 in tumor tissues and adjacent tissues from CRC patients and AOM/DSS-induced CRC mice were detected using qPCR and western blotting." (PMID 36739428, 2023). "The results showed that the expressions of FUT2, LC3-II, and p62 decreased in the tumor tissues of the FUT2 knockdown group compared with the A549 and NC groups." (PMID 36552800, 2022). "We carried out further verification of the effect of FUT2 on autophagy in subcutaneous tumor models." (PMID 36552800, 2022). "For this, we evaluated the general expression of fucosylation-related genes detected in tumour cells using gene sets associated with the GDP-Fuc synthesis (GMDS, TSTA3), fucosyltransferases (FUT2, FUT3, FUT4, FUT6) or both." (PMID 35017635, 2022). "In contrast, our study showed that FUT2 knockdown significantly abrogated cellular proliferation, adhesion, tumor formation in T47D, which implied a tissue-specific role of FUT2 in different tissues/cells." (PMID 30854233, 2019). "After tail vein injection of these cells into NOD/SCID mice, FUT1 and FUT2 overexpression enhanced tumor localization in the lungs by 2.56 fold and 5.3 fold, respectively of vector control cells as determined by luciferase luminescence." (PMID 30854233, 2019). "As shown in the xenografts mice model, mice were sacrificed at 6 weeks, and tumors were harvested, measured and weighted, the RNAi-FUT2 group showed significantly decreased tumor growth as compared with control xenografts (A549 group and NC group)." (PMID 29228607, 2017). "In short, both FUT1 and FUT2 are important for tumor growth in vitro and in vivo." (PMID 30854233, 2019). "FUT2-silencing in T47D dramatically reduced tumor volume by 95%." (PMID 30854233, 2019). "The indicator sensitivity of Lewis antigens would be significantly increased based on the determination of the FUT2/3 genotype, which may have wide application in tumor diagnosis." (PMID 29123975, 2017). "Finally, a fucosyltransferase inhibitor repressed the fucosylation modification of MCAM, promoting cell proliferation, invasion and tumor metastasis in Fut2-overexpression cells, indicating that fucosylation of MCAM might be a mediator of Fut2 in CRC." (PMID 36739428, 2023). "Additionally, the effect of FUT2 knockdown on tumor xenograft growth in nude mice was investigated." (PMID 29228607, 2017). "This was consistent with greater tumor mass in lungs as reflected by weight in mice injected with FUT1 and FUT2 overexpressing cells than that in vector control cells." (PMID 30854233, 2019).
tumor (continued). "In cells harvested from xenografted tumor of T47D and MCF7, silencing of FUT2 or FUT1 similarly reduced mammosphere formation by 75% and 65%, respectively, as compared to that in shLuc control." (PMID 30854233, 2019). "We examined the mRNA expression levels of the FUT1, FUT2, B3GALT5 and ST3GAL2 in tumor specimens of 135 HCC patients by qRT-PCR." (PMID 28883415, 2017). "Additionally, older patients with a tumor exhibited elevated FUT2, FUT3, and FUT8 coexpression with tumor-promoting IL6ST, IL22RA1, TGFB1, and TGFBR1 genes compared with young tumor." (PMID 38456503, 2024). "Compared with young patients with a tumor, we found that the epithelial subset cE03 showed elevated FUT2 and FUT3 and coexpression with tumor-promoting TGFB1 and interleukin 6 cytokine family signal transducer (IL6ST) gene expression in older patients with a tumor." (PMID 38456503, 2024). "In addition, we subcutaneously injected both WT and Fut2-overexpressed SW480 and HCT116 cells into nude mice and measured the tumor weight after 4 weeks." (PMID 36739428, 2023). "FUT1, FUT2, B3GNT2, GCNT2, and ST8SIA5 are involved in the blood group biosynthesis, a synthesis of blood group antigens process, which are glycan structures on cell surfaces that can influence tumour cell interactions with the TME, including immune system components." (PMID 39457550, 2024).
bacterial infection (5 papers, 2017 to 2025). "A study showed that mice deficient in Fut2 were significantly more vulnerable to bacterial infections, highlighting the key role of Fut2 in defending against infections." (PMID 39165572, 2024). "Three mutations were discovered in the FUT2 gene, which encodes a fucosyltransferase involved in protecting epithelium from bacterial infection." (PMID 29178652, 2017). "Like IL-22, LTα is also involved in the induction and maintenance of Fut2 expression, and Fut2 can subsequently catalyze epithelial fucosylation in the gastrointestinal tract, which has a role in preventing bacterial infection." (PMID 41467015, 2025).
intestinal diseases (5 papers, 2017 to 2025). "Growing evidence further suggests that the Fucosyltransferase 2 (FUT2) gene is a key risk factor for intestinal disease." (PMID 41020029, 2025). "Indeed, as discussed, the secretor status of FUT2 has shown a significant association with intestinal diseases." (PMID 35923409, 2022). "Finally, a recent study reported a novel inhibitor of Fut8 that could inhibit the malignance of CRC cells; therefore, we could assume that novel agonists of Fut2 may also be developed for Fut2-deficiency-induced intestinal disorders." (PMID 38550777, 2024). "Our results indicated the significance of Fut2-mediated α1,2-fucosylation in ISC aging through regulating mitochondrial functions, which provided new insight into stem-cell-based therapeutic strategy for age-associated intestinal diseases." (PMID 38550777, 2024). "Growing evidence and hypotheses support the involvement of FUT2 in the pathogenesis of many intestinal diseases." (PMID 35923409, 2022). "Fut2 manipulation with dietary fibers such as β2→1-fructans may therefore be an interesting approach to alleviate symptoms or frequency of intestinal diseases in the 80% of secretors." (PMID 28261212, 2017). "Therefore, there is a non-negligible association between the FUT2 gene and intestinal diseases including IBD, which is caused by RV and NoV." (PMID 35923409, 2022). "As the significance of Fut2-mediated α1,2-fucosylation in ISC aging was revealed, therapeutic strategies targeting fucosylation may be applicable regarding some age-related intestinal diseases in future studies." (PMID 38550777, 2024).
infectious disease (3 papers, 2018 to 2025). A disorder directly resulting from the presence and activity of a microbial, viral, or parasitic agent in humans. "The capacity to generate soluble ABH blood group antigens, dependent on the functionality of the FUT2 enzyme, represents an important modulator of infectious disease susceptibility in humans." (PMID 34532061, 2021).
metabolic disease (3 papers, 2020 to 2024). A congenital disorder (due to inherited enzyme abnormality) or acquired (due to failure of a metabolically important organ) disorder resulting from an abnormal metabolic process. "Evidence suggests that the expression patterns of FUT2 (Secretor gene) and FUT3 (Lewis gene) can play a role in the predisposition to metabolic diseases." (PMID 32722157, 2020).
adenocarcinoma (2 papers, 2017 to 2023). A common cancer characterized by the presence of malignant glandular cells. "The effect of FUT2 knockdown on cell migration and invasion in adenocarcinoma cells was determined by transwell assay." (PMID 29228607, 2017).
cardiovascular disease (2 papers, 2024). "Our results suggest that the rs6022662 FUT2 polymorphism may influence the risk of cardiovascular diseases." (PMID 38928269, 2024). "Individuals with MTHFR, FUT2, and COMT variants can be categorized into high- or low-risk groups for conditions like cardiovascular disease, cognitive dysfunction, or nutrient deficiencies." (PMID 39642577, 2024).
psychiatric disorder (2 papers, 2022 to 2023). A disorder characterized by behavioral and/or psychological abnormalities, often accompanied by physical symptoms. "Overall, pleiotropic variants between gastrointestinal tract diseases and psychiatric disorders were extensively distributed, with several loci especially highlighted between certain trait pairs, such as 1q32.1 (INAVA), 19q13.33 (FUT2), 11q23.2 (NCAM1), and 1p32.3 (LRP8)." (PMID 36753304, 2023).
respiratory disease (2 papers, 2023). "The finding that infant FUT2 status significantly impacted their microbiome is consistent with other studies on the FUT2 genotype and microbiome, which have typically been conducted in adult populations, including studies on healthy individuals and studies on gut and respiratory diseases." (PMID 36678342, 2023). "Novel signals at the FUT2 and mucin loci suggest that mucin fucosylation may be a driver of chronic sputum production even in the absence of diagnosed respiratory disease and provide genetic support for this pathway as a target for therapeutic intervention." (PMID 37263751, 2023).
FUT2 also shares sentences with these, for which no sentence is quoted: Allergy (5 papers); diabetes (3); Arthritis (2); chronic pancreatitis (2); gastric cancer (2); Hepatic steatosis (2); ovarian carcinoma (2); acute diarrhea (1); acute pancreatitis (1); alcoholic liver diseases (1); Alzheimer disease (1); Anxiety (1); atopic eczema (1); atrophic gastritis (1); bronchitis (1); central obesity (1); cholestasis (1); Chronic colitis (1); colorectal adenocarcinoma (1); coronary heart disease (1); cystic fibrosis (1); depression (1); Diarrhea (1); distal colitis (1); duodenal ulcer (1); eczema (1); endometriosis (1); enterocolitis (1); epidermoid carcinoma (1); essential hypertension (1).
A further 35 diseases each share a sentence with FUT2 in 1 paper.